IL10 (interleukin 10)
Diseases named in the same sentence as IL10 in open-access papers (continued):
Sharing a sentence is not in itself a finding about the gene and the disease.
tumor (continued). "The results showed that both anti-inflammatory cytokines, such as IL-4 and IL-10, were up-regulated in tumours derived from animals that had previous exposure with the EDC, while the expression of the pro-inflammatory counterpart (TNF-α and IFN-γ) was diminished." (PMID 31731436, 2019). "It was also that disruption from the interaction between IL-10 and it the receptors that may lead to enhanced inflammation which could promote tumor growth." (PMID 31351482, 2019). "On the other hand, IL-10 could also prevent or reduce tumour growth and metastasis via suppression of angiogenesis." (PMID 30947706, 2019). "sPD-1(soluble PD-1), interacting with PD-L1, could prevent PD-1 from binding with PD-L1 and promote effective tumor immunity, possibly resulting from decreased IL-10, TGF-β and increased IL-2 TNF-α and IFN-γ." (PMID 31708918, 2019). "In the pre-metastatic niche, MDSCs secrete IL-10 and IL-4, which may prime DCs for tolerance prior to tumor cell seeding." (PMID 31921140, 2019). "RNA-seq based gene expression analysis of astrocytes reveals a distinct astrocytic phenotype caused by the coexistence of microglia and astrocytes in the tumor environment, which leads to a large release of anti-inflammatory cytokines such as TGFβ, IL10 and G-CSF." (PMID 31186414, 2019). "As an immune-suppressive cytokine, IL-10 promotes tumor cell proliferation and metastasis." (PMID 31448052, 2019). "Astrocytes contacting tumor cells secrete cytokines that support tumor metastasis in the brain and contribute to an immunosuppressive microenvironment with high levels of anti-inflammatory cytokines such as IL-10, TGFβ and CSF." (PMID 31906065, 2019). "Multiple cytokines, including tumor necrosis factor (TNF)-α, interleukin (IL)-6, IL-17, IL-12, IL-23, IL-10, transforming growth factor (TGF)-β, and macrophage migration inhibitory factor, have been associated with human cancers and can promote or inhibit tumor development." (PMID 31043452, 2019). "In vivo, A2BR blockade also reversed immune suppression in the tumor microenvironment by reducing levels of IL-10, MCP-1, and MDSCs in melanoma lesions and increasing the frequency of CD8+ T lymphocytes and NK cells, and increasing the levels of Th1-like cytokines." (PMID 31739402, 2019). "Moreover, IL-10 has anti-inflammatory and pro-immunity functions which inhibits tumor promoting inflammation and induces CD8+ cells." (PMID 31653148, 2019). "Our data documented that NLGP may act as a potential immunotherapeutic drug that modify highly immunosuppressive TC-MSCs by downregulating their IL-10-secreting properties in tumor microenvironment." (PMID 31547863, 2019). "In addition, down-regulation of CCAT1 upregulated IL-10 production and tumor cell invasion, an effect that can be eliminated when co-transfected with miR-148a inhibitor." (PMID 31777603, 2019). "Specifically, utilizing a transforming growth factor –β (TGF-β)/oncogenic microRNA (miR)-21/tumor suppressor programmed cell death protein 4 (PDCD4) axis decorin downregulates the release of IL-10, which is an anti-inflammatory mediator and thus inhibits tumor growth." (PMID 31068944, 2019). "Although depletion of Tregs could enhance the CD4+ T cell response to the vaccine cells, Tregs might also improve anti-tumor immunity by promoting the generation of CD8+ T memory cells via production of IL-10." (PMID 30956760, 2019). "These two helper T cell subtypes were co-enriched in the same patient clusters, despite being thought to be associated with different processes; that is, Th1 cells induce IFNG expression and anti-tumor effects while Th2 release IL-4 and IL-10, which help allow for tumor-escape." (PMID 30956762, 2019). "Our data suggest that S1P1 promotes tumor-associated (i)Treg expansion in a cell type-specific manner and that this effect is associated with the activation of TGF-β signaling and the production of TGF-β and IL-10 in BC cells." (PMID 30718502, 2019).
tumor (continued). "For instance, PGE2 increase Th17 through the production of IL-23 and IL-1β by DCs and macrophages, while it can also induce expansion of IL-10 producing Treg type-1 cells (Tr1) as a result of tumor cells secretion as well as expression of COX2/PGE2 by Treg cells." (PMID 31024835, 2019). "Moreover, IL-10 is a key immunoregulatory mediator which suppresses T cell functions and induces regulatory T cell development, thereby promoting tumor immune evasion." (PMID 31013891, 2019). "While there is evidence of direct Tregs suppression of effector T cells via cell-to-cell contact, the impact of Tregs on the tumor microenvironment and immune cells from the secretion of TGFβ and IL-10 is a major contributor to the immunosuppressive environment of tumors." (PMID 31998326, 2019). "IL-10 and TGFβ could impair the capacity of pDCs to produce IFNα and potentially create a vicious cycle intensifying the immunosuppressive effect of the tumor." (PMID 30987228, 2019). "Whether produced by DC themselves or present in the tumour microenvironment, IL-10 conditions human DCs to acquire a tolerogenic phenotype favouring the induction of T cell anergy and suppressive function." (PMID 30717461, 2019). "Increases in PD-L1 expression can occur on SCC cells as a result of mutations in tumor cell signaling pathways or exposure of tumor cells to inflammatory cytokines IL-1, IL-6, GM-CSF, IFNγ, TNFα, and VEGF and the gamma-chain cytokines IL-2, IL-7, IL-10, IL-15, and IL-21." (PMID 31554151, 2019). "Membrane-bound TGF-beta 1, VEGF, and IL-10 on MDSCs could induce tumor cells to undergo EMT leading to tumor cell metastases." (PMID 31552179, 2019). "Notably, TRAPs-elicited CD4+ T cells inhibited CD4+ and CD8+ effector T cell function in an IL-6- and IL-10-dependent manner and induced IL-10-producing regulatory B cells (Bregs) via IL-6, IL-10 and IL-21, thereby promoting tumor growth and metastasis." (PMID 31300052, 2019). "Furthermore, these regulatory DCs can elicit the activation of regulatory T cells (Tregs) and downregulate the recruitment of CTLs to the tumor site by secreting suppressive cytokines such as IL-10 and TGF-β." (PMID 30991681, 2019). "Overwhelming evidence suggests that interaction of PD-L1/PD-1 in the tumor microenvironment promotes T cell dysfunction, exhaustion, apoptosis, neutralization, and elaboration of IL-10 in a tumor mass creating a state of resistance from cytotoxic T cell (CD8+)-mediated tumor cell killing." (PMID 31488176, 2019). "Indeed, IL-10 remains controversial in the context of tumor formation, due to the often opposing downstream effects of α/β receptor binding and complex layers of regulation." (PMID 31842362, 2019). "These MØs express CD163 and M2-specific markers (increased expression of FOLR2 and MAF and reduced expression of ActA), and show an upregulated expression of different factors that favour tumour progression (including, among others, IL-10, TGF-β, IL-6, IL-8, IDO1, COX2 and GAL-1)." (PMID 31337120, 2019). "On the one hand, IL-10 impairs antitumor immunity and promotes tumor growth in mouse models." (PMID 31379886, 2019). "The ability of Plasmodium infection to perturb ROS generation, inhibit arginase activity, and downregulate iNOS and IL-10 expression clearly demonstrates the potential benefits of the Plasmodium-mediated targeting of immunosuppressive cells in the tumor microenvironment." (PMID 30979375, 2019). "IL-10 is a pleiotropic cytokine that exhibits both tumor-promoting and inhibitory properties." (PMID 31700993, 2019). "To investigate factors contributing to DC dysfunction in GBM, we tested the hypothesis that Dex or GBM tumor lysate (TL) altered the IL-12/IL-10 cytokine balance of cDC2." (PMID 31143512, 2019). "Therefore, a recipe consisting of IL-4, IL-10, M-CSF, and tumor-conditioned media was utilized in this study to generate monocyte-derived TAM in vitro." (PMID 31138333, 2019).
tumor (continued). "Indeed, S1P1 enhances the tumor-associated induction of (i)Tregs from naïve T cells by increasing the production of TGF-β and IL-10 in the tumor environment." (PMID 30718502, 2019). "Interestingly, mice treated by gavage with fish oil rich in omega-3, soybean oil rich in omega-6, or the mixture between these oils with a ratio of 1:1 showed higher IL-10 levels in the tumor microenvironment compared to the control group." (PMID 31374840, 2019). "Afterwards, the expression levels of 12 cytokines including IL-1a, IL-1b, IL-2, IL-4, IL-6, IL-8, IL-10, IL-12, IL-17A, TNFα, IFNγ and GM-CSF in secretome of hWJ-MSCs alone as well as in supernatant of tumor cells before and after treatment with hWJ-MSCs secretome were evaluated." (PMID 31857970, 2019). "The anti-interleukin-10 (IL-10) antibody partially blocked this increase, suggesting that TAMs may trigger an increase in the population of FoxP3+ Treg cells in the tumor, thereby promoting the progression of HCC." (PMID 31464625, 2019). "Furthermore, GB-induced CMA in PC enhances secretion of the anti-inflammatory cytokines TGFβ and IL-10 to promote an immunosuppressive phenotype that leads to failed tumor antigen-specific T cell responses, facilitating tumor tolerance." (PMID 31906065, 2019). "Further, up-regulation of fatty-acid synthase (FASN) by M-CSF in tumor infiltrating myeloid cells was required for PPARβ/δ-dependent expression of immunosuppressive and pro-angiogenic genes (e.g. IL-10, Arg1 and VEGF) and consequent promotion of tumor progression, in a model of Lewis lung cancer." (PMID 31535085, 2019). "IL-10 can be expressed by MDSCs as a stimulator for tumor progression." (PMID 31552179, 2019). "Initially it was assumed that IL-10 is only produced by immune cells, further studies revealed that IL-10 is produced by non-immune cells as well, including keratinocytes, epithelial cells and tumor cells for instance." (PMID 31443525, 2019). "Given the prominent role of IL-10 in tumor immunology and the emerging role of CD14+HLA-DRlowMDSC in human diseases, these findings may also have a biologically significant counterpart." (PMID 31316520, 2019). "Notably caerin peptides were able to increase the survival time of TC-1 tumour bearing mice after therapeutic vaccination with a HPV16E7 peptide-based vaccine containing IL-10 inhibitor, via recruiting increased levels of T cells to the tumour site." (PMID 31277636, 2019). "Tumor-infiltrating Tregs produce IL-10 and TGFβ, which further support tumor progression." (PMID 30987228, 2019). "However, our results also indicate that the tumor microenvironmental immune profile, defined by IL10 or PTGS2 gene expression levels, seems to alter the prognostic potential of CD20/MS4A1." (PMID 30879106, 2019). "Similarly, IL-4 and IL-13 secreted by tumor resident Th2 cells or IL-10 released by Treg and B cells induce M2-like TAM differentiation." (PMID 30853959, 2019). "The ability of UV to suppress CHS responses as well as the ability to promote B16F10 tumor growth may be mediated through similar mechanisms that are dependent on immune tolerance-inducing signaling by interleukin-10 and CD25+ T-cells." (PMID 31212694, 2019). "Glucomannan could re-energize the immune system to attack the tumor cells by decreasing IL-10 level and promoting the production of IFN-γ in tumor sites." (PMID 31507423, 2019). "Pro-tumor functions of TAMs are the result of a macrophage polarization with a particular cytokine profile (macrophage colony-stimulating factor (M-CSF), IL-4, IL-13, IL-10, Prostaglandin E2 (PGE2)) of the TME." (PMID 31547627, 2019). "Taking these findings together, the 1,2-DHX-dependent increase in TNF-α and decrease in IL-10 detection may contribute to tumor regression, although the TGF-β1 increase seems to contradict the xanthone antitumor effects." (PMID 31167479, 2019).
tumor (continued). "It was suggested that Foxp3+CD4+ T cells might in fact help to prevent or delay inflammation-mediated tumour development, as supported by the presence of remarkably higher levels of anti-inflammatory IL-10 from the serum samples of NSCLC patient." (PMID 30944831, 2019). "In one of the earliest reports of tumor-mediated DC tolerization, progressive melanoma tissues refractory to a chemoimmunotherapy regimen were shown to inhibit DC-dependent T cell proliferation via the IL-10 cytokine." (PMID 31921140, 2019). "Ex vivo experiments with tumor associated macrophages showed that SW could partially modulate macrophage phenotype, decreasing CCL2 secretion and impairing IL-10 and IL-6 upregulation, which prompted us to proceed to in vivo tests." (PMID 30840689, 2019). "The conventional opinions hold that TAMs are one of the M2‐like macrophages due to its high expression of antiinflammatory marker genes, such as interleukin‐10 (IL‐10) and IL‐1 receptor alpha (IL‐1Ra), which make a huge contribution to tumor growth and the subsequent development." (PMID 31222971, 2019). "In addition, the upregulation of PDL1 expression decreased the expression of proinflammatory cytokines (IFN‐γ, IL‐2, and TNF‐α) in mouse serum and tumor tissue samples and increased the expression of anti‐inflammatory cytokines (IL‐10)." (PMID 31557409, 2019). "Similarly, we noted a decline in IL-10 following the resection with the RF-based device HabibTM 4X, which not only directly suppresses cytotoxic T-cells and NK cells but also promotes tumour progression and a poor prognosis." (PMID 30893948, 2019). "All these data seem to indicate that the non-expression of pro-inflammatory cytokines (such as IL-1β and IL-6), together with the expression of an anti-inflammatory cytokine (such as IL-10) could contribute to tumor immune escape." (PMID 31086100, 2019). "We report that the acquisition of tumor aggressiveness in patients is dependent on close associations prevailing between NOS2 and IL-10 synthesis and between IL-17A, TGF-β, and MMP-9 and identifies IL-17A as a possible key predictor of LSCC aggressiveness and resistance to therapy." (PMID 31885577, 2019). "The PD1+ tumor-associated macrophages (PD1+ TAMs) displayed surface pattern and function akin to M2: a substantial enhancement in CD206 and IL-10 expression; a specific reduction in HLA-DR, CD64, and IL-12 expression; and a significant increase in the ability to inhibit CD8+ T-cell proliferation." (PMID 30796203, 2019). "Moreover, tumor cells themselves can secrete immunosuppressive substances (such as interleukin [IL]-4 and IL-10), which can reduce the body's response to them, thus facilitating their growth and metastasis." (PMID 31651881, 2019). "This immune suppressive population substantially prevents antitumor CD8+ T cells in vitro, while supports the tumor growth and progression via IL-10 production as well as cell to cell contact and also is associated with advanced stages of the disease and reduced survival." (PMID 31024835, 2019). "DC maturation is inhibited in many cancers, as a consequence of secretion of tumor cell-derived immunosuppressive factors, such as IL-10, transforming growth factor (TGF)-β, IL-6, prostaglandin E2 (PGE2) and granulocyte-macrophage colony-stimulating factor (GM-CSF)." (PMID 31428574, 2019). "In addition to IL‐8, we also found that expression of the chemokines MIF and IL‐10, which have been shown to mediate tumour‐promoting crosstalk between tumours and the tumour microenvironment, was increased following ZNF143 knockdown." (PMID 30933430, 2019). "Moreover, increased levels of interleukin (IL)-10 were detected in tumours of treated mice, that were accompanied by decreased levels of IFNγ." (PMID 29988113, 2019). "Tumor-associated macrophages (TAMs) are subdivided into two subsets, M1 and M2 macrophages, based on their capacity to express or produce Nitric Oxide Synthase/IL-12/TNF-α or arginase-1/IL-10/TGF-β, respectively." (PMID 31480382, 2019).
tumor (continued). "Therefore, over regulation of IL-10 production by tumor cells promotes tumor progression through the escape of immunosurveillance performed by NK, CD4, and CD8 lymphocytes." (PMID 31737570, 2019). "Furthermore, the expressions of MMP-2 and VEGF involved in metastasis, as well as inflammatory genes IL-1β, IL-6 and IL-10, showed dose-dependent decrease in tumor tissue after cisplatin exposure." (PMID 32257905, 2019). "Moreover, caerin 1.1 and 1.9 increased the efficacy of a therapeutic vaccine containing IL-10 inhibitor in the TC-1 mice tumour model by increasing the survival time of TC-1 tumour bearing mice." (PMID 31277636, 2019). "The release of immunosuppressive cytokines, for example IL-10, may have an important role by impairing tumor cell recognition." (PMID 30766448, 2019). "These soluble factors include Reg3 g, IL‐6, and IL‐10 in tumor‐conditioned medium." (PMID 30628173, 2019). "IL-10 triggers anticancer immunity in the tumor microenvironment." (PMID 31215439, 2019). "Conversely, M2 macrophages represent tumor-supportive macrophages and participate in polarized Th2 immune responses, via secreting immunosuppressive cytokines IL-10 and TGF-β, downregulation of antigen-presenting molecules, including MHC II, CD80, and CD86, and decreasing phagocytic capacity." (PMID 30034397, 2018). "In addition, tumor-derived IL-18 or rIL-18 enhanced B-cell proliferation and IL-10 production in vitro and in vivo." (PMID 29599908, 2018). "Novel cancer treatments based on IL-10 and IL-4 antibodies could pave the way for tumor elimination despite a worst-case scenario at the start of treatment consisting of a highly immunosuppressive, angiogenic and polarized tumor microenvironment." (PMID 35847834, 2018). "Mono-association of NC101 led to enhanced tumor multiplicity and invasion in AOM-treated germ-free Il10-/- mice, which was decreased in AOM-treated germ-free Il10-/- mice mono-associated with an isogenic mutant deficient for pks island (NC101Δpks), without altering colonic inflammation." (PMID 30295289, 2018). "Furthermore, HCQ up-regulated the expression of Ifng and down-regulated the mRNA levels of Tgfb1 and IL10 in tumour-infiltrating CD8+ T cell from tumour tissues." (PMID 30373678, 2018). "Importantly, IL-2/CD40 reduced expression of a number of regulatory markers on young and elderly TDLN CD11c+ cells including: CD73, TGF-β, CD39 and IL-10, relative to age-matched untreated tumor-bearing mice." (PMID 30560130, 2018). "Besides being involved in T cell education, several studies also reported on downregulation of MHC class II expression on antigen-presenting cells (APCs) and of MHC class I on tumor cells in cancer patients with elevated IL-10 levels in serum or tumors." (PMID 29988341, 2018). "However, ELSs were found in the OxP-treated CT26-FL3 tumor model, with abundant T cells, DCs, macrophages, NK cells, Tregs, MDSCs, as well as increased expression of immunosuppressive PD-L1 and IL-10." (PMID 29884866, 2018). "Therefore, to consider IL-10 as a target in tumor immunotherapy, the immunological context has to be taken into account." (PMID 30233565, 2018). "Furthermore, young, but not elderly, IL-2/CD40-treated mice demonstrated additional reductions in other regulatory markers expressed by tumor-associated CD4+ T cells, including ICOS and IL-10." (PMID 30560130, 2018). "We also examined the expression of cytokines and gene signatures associated with inflammation and tumor pathogenesis of colon tissues and found that Il10 expression was not significantly induced by B. fragilis in either wild-type or Tlr2−/− mice." (PMID 30429227, 2018). "These PD1+ tumor-associated macrophages (TAMs) exhibited an M2-like surface profile, with a significant increase in the expression of CD206, IL-10, and CCL1, and a clear decrease in the expression of MHC class II, CD64, and IL-12 and the ability to phagocytose ovalbumin." (PMID 29799520, 2018).